ITGA6 (integrin subunit alpha 6)
Diseases named in the same sentence as ITGA6 in open-access papers (continued):
Sharing a sentence is not in itself a finding about the gene and the disease.
tumor (continued). "Similarly, in human umbilical cord-derived MSCs (hUC-MSCs), transfection with miR-3940-5p mimics led to EVs that suppressed EMT, invasion, metastasis, and tumor progression by targeting integrin subunit alpha 6 (ITGA6) and inhibiting the transforming growth factor beta 1(TGF-β1) pathway." (PMID 41254732, 2025). "Moreover, ITGA6 can promote the growth of tumor-initiating cells (TICs)." (PMID 39239559, 2024). "Hence, the identified subpopulation of tumor cells exhibiting simultaneous expression of ITGA6 and ITGB4 may serve as a viable target for ongoing therapeutic developments." (PMID 38250718, 2024). "More intriguingly, ITGA6 also showed strong positive correlations with pro-tumorigenic immune cell types such as regulatory T cells (Tregs), CAFs, and myeloid-derived suppressor cells (MDSCs), highlighting a potential role in shaping a more permissive and supportive tumor microenvironment." (PMID 37627184, 2023). "NRP1 inhibition suppressed expression of the mesenchymal and stem cell markers ZEB1 and ITGA6, respectively, compromised spheroid-initiating capacity and exerted potent anti-tumor effects on claudin-low orthotopic xenografts (12.8-fold reduction in endpoint tumor volume)." (PMID 35078508, 2022). "To figure out the mechanism underlying the tumor-suppressive effect of FTO expression on BCa cells, we detected the expressions of the known differentially m6A methylated genes, including MALAT1, CSNK2A2, ITGA6, and NOTCH1, which were found to correlate with BCa progression in previous studies." (PMID 34499008, 2021). "This study suggests a promising KDM5B‐targeted therapy for HCC patients and also proposes that a KDM5B/miR‐448/YTHDF3/ITGA6 axis is involved in the occurrence and development of this cancer, which could constitute an important tumour‐related molecular mechanism." (PMID 33829656, 2021). "Additionally, the ITGA6 assessment of the xenografted tumours showed comparable results by IHC." (PMID 29416013, 2018). "Further analysis of the expression relationship between tumor tissues and adjacent paired tissues of ITGA3, ITGA5, and ITGA6 in HNSC reveals that the expressions of ITGA3, ITGA5, and ITGA6 are significantly increased in tumor tissues." (PMID 41602372, 2026). "When exosomes enriched with ITGA6 or ITGB2 protein were co-cultured with mouse ovarian cells, we observed that the ovarian cells uptook more tumor-derived ITGA6- or ITGB2-high exosomes compared to those derived from control cells." (PMID 40860157, 2025). "This subtype exhibited enhanced basal‐like and stemness features and showed high LAMC2 expression, which activated laminin‐integrin signaling via ITGA6/ITGB4, promoting tumor invasiveness." (PMID 40470730, 2025). "Focused on this cluster number “3”, cells from the three samples were found to express some epithelial/tumor markers at distinct levels, with markers including EPCAM, CD44, KRT8, ITGA6, and CLDN4." (PMID 41440935, 2025). "ITGA6 is a transmembrane protein involved in cell surface adhesion and signaling as well as in the regulation of proliferation, tumor invasion, and metastasis; similar to THBS3 and THBS4, ITGA6 is also expressed in the skin of sheep." (PMID 39913466, 2025). "The four-gene signature (CLN6, GMPR, AP1S2, ITGA6) and their validated roles in proliferation/migration (e.g., CLN6 knockdown suppressing tumor growth) provide novel therapeutic targets." (PMID 40821828, 2025). "We observed significantly higher expression of METTL16, ITPR1, CAPN2, ITGA3, RAC1, ITGA6, and CHMP28 in tumor samples (P<0.05)." (PMID 39434688, 2024). "ITGA6 is an extracellular integrin receptor that has been found to promote EMT and tumour invasion and metastasis." (PMID 38783078, 2024). "Through targeting of ITGA6, a gene involved in this PFA-specific chromatin cluster, we demonstrated the importance of integrin signaling for maintained tumor growth, specifically in PFA tumors." (PMID 37085539, 2023).
tumor (continued). "This research highlights the potential of ITGA6 as an early HCC detection marker and its role in the tumor microenvironment, paving the way for new strategies in HCC management." (PMID 37627184, 2023). "In particular, the interaction between Midkine (MDK, secreted by tumor cells) and a number of MDK-receptors (ITGA4, ITGA6, ITGB1, NCL, LRP1) on CD8+ T cells appears to be a recurrent immunosuppressive pathway seen across all three patients." (PMID 36973261, 2023). "Reduced expression of eight immune‐related genes (IRGs) (NT5E, THRA, RBP1, TLR4, ITGA6, BMPR1B, ITGAV, SSTR1) in tumor strongly predicted better quality of prognosis, both in our patient cohort and in TCGA‐HNSC cohort." (PMID 37392167, 2023). "Our study elucidates the potential of ITGA6 as a blood-based marker for HCC early detection and diagnosis and its complex interplay with the tumor microenvironment." (PMID 37627184, 2023). "On the contrary, the low expression of ITGA6 can impair the activity of the PI3K/AKT pathway to exert a tumor‐suppressive function." (PMID 37555363, 2023). "This revealed that GPx2 KD further enriched cluster 5 in basal/mesenchymal-like genes (KRT14, ITGA6, FGFR1, COLA9A3, S100s) relative to cluster 5 in control tumor." (PMID 35193955, 2022). "Tumor samples with more than 4 mm thickness exhibited significantly lower relative expression levels of ITGA3, ITGA6, ITGA9, ITGAV, and ITGB1 than samples belonging to the 2–4 mm Breslow thickness category (Mann–Whitney test, p < 0.05)." (PMID 36091936, 2022). "ARID3B, CXCR1, GATS, Itga6, Shh, SLC27A5, STC2, and VEGF play an important role in cell proliferation and tumor progression or metastasis." (PMID 35875133, 2022). "These cells highly expressed the integrin family genes associated with the cell adhesion molecule pathway in contrast to epithelial tumor cells, such as ITGA2, ITGA3, ITGA5, ITGA6, and ITGAV, which were among the top-ranking DEGs." (PMID 36553542, 2022). "We next verified the protein levels of the integrin α‐subunits suggested to be differentially represented between samples at the mRNA level, including ITGA2, ITGA3, ITGA4, ITGA6, ITGA11, and ITGAV using 10 paired (tumour and adjacent) ESCC patient tissues." (PMID 34709754, 2021). "Top upregulated master regulators in the tumor, as compared to the parent cells, include ZEB2 and PHLDA1; while top downregulated master regulators include AR, AHR, and ITGA6." (PMID 33808801, 2021). "Results showed that ITGAV (10/10), ITGA2 (7/10), ITGA3 (8/9), ITGA4 (7/10), ITGA6 (7/8), and ITGA11 (7/9) protein levels were increased in tumour tissues compared with adjacent tissues." (PMID 34709754, 2021). "Our previous studies showed that certain integrins are controlled directly by tumor-suppressive miRNAs (e.g., miR-29-family, miR-150, and miR-199a) and that the activation of signaling mediated by ITGA3/ITGB1 and ITGA6 enhances the aggressiveness of HNSCC." (PMID 34576110, 2021). "Integrin and adhesion related genes including ITGA2, ITGA6, and ICAM5 were changed by −6.12, −2.75, and −5.77-fold, respectively, comparing tumor to parent cells." (PMID 33808801, 2021). "The results showed that up‐regulation of KDM5B increased the size and weight of tumours and accelerated their growth, which was neutralized by oe‐KDM5B + sh‐ITGA6 treatment." (PMID 33829656, 2021). "Compared to the parent LNCaP cells, expression of AR, AHR, CDH1, CXCR7, FLNA, ITGA6, and UGT2B15 in tumor was significantly inhibited." (PMID 33808801, 2021). "Results illustrated that ITGA2, ITGA3, ITGA4, ITGA6, ITGA11, and ITGAV transcripts were increased in ESCC tumour tissues (n = 95) compared with normal tissues (n = 11)." (PMID 34709754, 2021). "Based on these intriguing results, this is the first time ever that PSMC2 is pinpointed as a tumor promotor to interfere HCC development and progression via interacting with ITGA6 directly." (PMID 34413286, 2021).
tumor (continued). "The complex that consists of integrin subunit α6 (ITGA6) and subunit β4 (ITGB4) and sequentially interacts with laminin and kindlin-3 (FERMT3) is involved in tumorigenesis by modulating tumor cell–ECM interaction." (PMID 32326232, 2020). "Several key proteins such as MAP2K1, ITGB4, ITGA6, PTPN6, FMNL1, ANXA1, and MMP9 that modulate cell motility and tumor cell invasion were upregulated in MIBUC." (PMID 32326232, 2020). "It has tumor suppressor effect via inhibiting proliferation by targeting KMT5a (Histone-Lysine N-Methyltransferase KMT5A) and ITGA6 (Integrin, Alpha 6)." (PMID 30945144, 2019). "On the other hand, comprehensive functional experiments are needed: eg it will be interesting to select CD44+/CD133+/ITGA6+/CD36+ cells and to evaluate their tumor formation capacity in NOD‐SCID mice brains." (PMID 30467961, 2019). "Integrin alpha 6 (ITGA6) is also up-regulated in LUSC in our study and other members of the ITGA family classified either as oncogenes or tumor suppressors." (PMID 31429720, 2019). "Our results further indicated that miR-143-3p inactivated the MAPK/ERK and PI3K/AKT/STAT3 pathways in GBC cells by directly targeting ITGA6, resulting in a decrease in PLGF and the development of GBC angiogenesis and tumour growth." (PMID 29416013, 2018). "Differential expression of seven of these genes (CFD, ALDH18A1, CHKA, DDIT3, ITGA6, PSPH and SQLE) was replicated in another set of 12 paired NASH-HCCs and adjacent non-tumor livers by RT-qPCR (all P < 0.05 by paired t test)." (PMID 30367044, 2018). "Intriguingly, some of these molecules are related to oncogenesis and tumour progression/metastasis, namely, HRAS, KRAS, TGFBR1, TGFBR2, RB1, ITGA6, ITGB4, mTOR, TSC2 and APLP2." (PMID 30258067, 2018). "ITGA6 is a major component of the ECM signalling pathway, which reportedly promotes tumour angiogenesis." (PMID 29416013, 2018). "miR-140 also contributes to tumor suppressive effect by targeting COL4A1, ITGA6 and MARCKSL1 in breast cancer." (PMID 29162923, 2017). "We identify ITGA6 as a novel HIF-dependent target gene that controls stem-like cell phenotypes and tumor cell invasion in pre-clinical models of metastatic breast cancer." (PMID 27001172, 2016). "Itga6 mRNA levels were compared in HIF-1 wild type (WT) and knockout (KO) PyMT tumor cells cultured at normoxia or hypoxia by quantitative real-time PCR (qRT-PCR)." (PMID 27001172, 2016). "MiR-29 family has also demonstrated its tumor suppressor role by targeting laminin γ2 (LAMC2) and α6 integrin (ITGA6) resulting in the inhibition of cell migration and invasion in HNSCC cell line (SAS and FaDu)." (PMID 27391030, 2016). "Significant differences in GS were identified in relation to the expression profiles of ITGAV1, ITGA3, ITGA6, SPARC, MMP9, and MMP16, markers that were detected in the tumour samples examined." (PMID 26674523, 2015). "Others are more distinctive of a "state", e.g. distribution of cytokeratins and down-regulation of certain integrins (ITGA6/ITGB4, ITGA7) in all the tumour-derived cell lines." (PMID 16626496, 2006). "This suggests that elevated expression levels of ITGA5 and ITGA6 may result in decreased infiltration of inhibitory immune cells in the TME, thereby promoting tumor progression." (PMID 41602372, 2026). "In ITGA6–WFL, the signal‐to‐background levels were lower than in other ITGA6 assays, which suggests that ITGA6 glycovariants with a GalNAc–glycan structure are not common in HNSCC tumor tissue." (PMID 40287842, 2025). "Notably, RARγ peaks were highly enriched near genes involved in cell surface signaling and adhesion, including SERPINE1, ITGB3, ITGA6, and COL4A2, which are known to control both epithelial plasticity and tumor progression." (PMID 41274504, 2025).
tumor (continued). "Our observations further indicate that Tip-like ECs may actively respond to PARs signaling cues from Malignant Cluster01 tumor cells, particularly serving as receivers via the MDK-(ITGA6+ITGB1) ligand-receptor pairs." (PMID 39944338, 2025). "Differential gene expression analysis demonstrated that Tum_1 tumor cells predominantly expressed basal cell marker genes such as KRT14, KRT5, and KRT15, and exhibited high levels of genes related to cell adhesion, including ITGB4 and ITGA6." (PMID 40470730, 2025). "rTAM also expressed distinct integrin transcripts, including Itga6, Itgb1, and Itgb5, which bind ECM components including laminin and collagen, and may facilitate interaction at the tumour-normal interface." (PMID 40523200, 2025). "Only the ITGB4 and ITGA6-expressed CTCs showed differentially expressed genes and the maximum number of increased tumor progression-related genes (26/36) compared to the no integrin CTCs." (PMID 38250718, 2024). "The results of RT-qPCR and Western blot demonstrated an enhancement in the mRNA and protein expression of SMAD3, ITGA6, PI3K protein expression and Akt phosphorylation level yet unchanged total Akt protein expression in the tumor tissues of mice treated with H460/oe-SMAD3 + Gy or H460/CAFs + Gy." (PMID 38493128, 2024). "Additionally, Midkine (MDK) released from tumour cells interacted with SDC4, SDC1, NCL, ITGA4, ITGA6 and ITGB1 on immune cluster." (PMID 39187937, 2024). "Furthermore, both integrins (ITGA6 and ITGB1) were knocked down at the same time to examine the tumor suppressor effects, e.g., cell proliferation and migration, and invasive abilities." (PMID 34199886, 2021). "Besides, the expression of KDM5B, miR‐448, YTHDF3 and ITGA6 in mouse tumour tissues was measured by RT‐qPCR; the results revealed that up‐regulation of KDM5B reduced miR‐448 expression, while up‐regulating KDM5B, YTHDF3 and ITGA6 expression." (PMID 33829656, 2021). "Tumor-promoting roles of MAP3K6, PAK1, ALCAM and ITGA6 have been reported, thus their upregulation may also function in the development of NASH-related HCC." (PMID 30367044, 2018). "In conclusion, miR-143-3p suppresses tumour angiogenesis and growth of GBC through the ITGA6/PI3K/AKT/PLGF pathways and may be a novel molecular therapeutic target for GBC." (PMID 29416013, 2018). "Established GICs clearly display mesenchymal traits, greater clonogenic capacity, have greater self-renewal and tumorigenic capability, and express more L1CAM, CD44, CD133 and ITGA6 compared to the non-GIC tumor bulk cells." (PMID 29088733, 2017). "When patient samples were stratified by the highest and lowest quartiles of tumor ITGA6 expression [GEO: GSE1992], higher levels of ITGA6 expression predicted significantly shorter overall survival (OS) and recurrence-free survival (RFS) as compared to patients with low ITGA6 expression." (PMID 27001172, 2016). "A direct contribution of ITGA6 to breast CSC or TIC potential was shown in mammospheres derived from MCF-7 cells, which express higher levels of CD49f relative to bulk cells; knockdown of ITGA6 also blocked tumor growth in vivo." (PMID 27001172, 2016). "Similarly, in comparing the scores from the histological analyses performed in the present study, correlations between tumour type (mucinous or adenocarcinomas NOS) and the ITGA5 and ITGA6 integrins were observed (p < 0.001)." (PMID 26674523, 2015). "We next randomly selected 8 genes aberrantly expressed in HCCs that had aberrant DNA methylation (CR1, ESR1, PTPN13, and SOCS2) or SCNA (C8A, CXCL14, ITGA6 and MARCO) to validate the array-based results in an independent sample set consisting 47 HCCs and paired non-tumor specimens." (PMID 25965583, 2015). "Further, although highly expressed in the tumour tissues, ITGA6 seems not to be involved in HPV infection due to the low HPV infection rate." (PMID 23570247, 2013).
tumor (continued). "Additionally, laminin encoded by LAMA4, LAMB1, and LAMB2 mediate adhesion through Integrin binding—specifically the Integrin α6β4, composed of integrin α6 (ITGA6) and Integrin β4 (ITGB4)—is suggested to be essential for tumor development and progression, promoting pro-cancer signaling pathways." (PMID 40333631, 2025). "Altogether, our data indicated that ITGA6, secreted by PT-res cells, modifies the transcriptional program of PT-sen and mesothelial cells, enhancing adhesion, invasion, and metastatic growth of EOC, by acting not only on tumor cells but also on the local microenvironment." (PMID 38658801, 2024). "Therefore, CTCs with the ITGA6 and ITGB4 expression have a set of potencies that could lead to tumor cells spread across the body." (PMID 38250718, 2024). "This suggests that ITGA6 may not be actively involved in recruiting or modulating these immune effectors, which are crucial for anti-tumor immunity." (PMID 37627184, 2023). "We further compared the relative expression of these molecules in 14 cancer types containing paired tumor and normal samples and found that approximately half of the autophagy regulators showed elevated expression in different cancers, including BIRC5, RIPK2, MET, ITGA6, BCL2L1, CASP4, etc.." (PMID 36261830, 2022). "In addition, hBM-MSC-Exo and hUC-MSC-Exo containing tumor-suppressive miRs (miR-3940-5p/miR-22-3p/miR‐16‐5p) have been shown to suppress proliferation, migration, and invasion of CRC cells via regulation of RAP2B/PI3K/AKT signaling pathway and ITGA2/ITGA6." (PMID 35365226, 2022). "In addition, ITGA6 is relevant for binding laminin‐111 and ‐211, while ITGA7 is more relevant for laminin‐211, further supporting the role of laminin‐111 and ‐211 in SHH tumours." (PMID 33206391, 2021). "Furthermore, in HPV-positive HNSCC cells, ITGA6 can regulate the stemness of tumor cells through the AKT pathway, affecting the size and number of tumor cell spheres formed in HPV-positive HNSCC cells and enhancing the self-renewal capacity of tumor stem cells." (PMID 39239559, 2024). "Evaluation of the differential gene expression revealed that only CTCs with ITGA6 and ITGB4 expression demonstrated increased expression of 14 tumor-progression related genes compared to the no integrins CTCs, almost half of which were related to EMT." (PMID 38250718, 2024). "Using TIMER 2.0,35 we found significant negative correlations between the expressions of ITGA6 and CD73 with CD8+ T cell and plasma cell infiltration in tumor." (PMID 37392167, 2023). "Our data have also shown negative correlations between the expressions of CD73 and ITGA6 genes and the proportions of CD8+ T cells and B cells in the tumor." (PMID 37392167, 2023). "Although we cannot exclude that ITGA6 is involved in HPV uptake, our data indicate that its presence and upregulation in the tumour samples do not play a rate limiting role in the establishment of HPV infection." (PMID 23570247, 2013). "We examined the expressions of ITGA6 and ITGB2 across these samples and found that ITGA6, but not ITGB2, was highly expressed in fibroblasts in OM compared to AT and PT, supporting that tumor-derived ITGA6-high exosomes are predominantly uptaken by fibroblasts in ovarian tissues." (PMID 40860157, 2025).